CLDN1 (claudin 1)
Description:
Claudins function as major constituents of the tight junction complexes that regulate the permeability of epithelia. While some claudin family members play essential roles in the formation of impermeable barriers, others mediate the permeability to ions and small molecules. Often, several claudin family members are coexpressed and interact with each other, and this determines the overall permeability. CLDN1 is required to prevent the paracellular diffusion of small molecules through tight junctions in the epidermis and is required for the normal barrier function of the skin. Required for normal water homeostasis and to prevent excessive water loss through the skin, probably via an indirect effect on the expression levels of other proteins, since CLDN1 itself seems to be dispensable for water barrier formation in keratinocyte tight junctions. (Microbial infection) Acts as a co-receptor for hepatitis C virus (HCV) in hepatocytes. Associates with CD81 and the CLDN1-CD81 receptor complex is essential for HCV entry into host cell. Acts as a receptor for dengue virus.
Synonyms: CLD1; SEMP1; ILVASC
Tractability: Antibody: UniProt places it where antibodies can reach, with high confidence; its Gene Ontology location is reachable by antibodies, with high confidence; UniProt predicts a signal peptide or a membrane-spanning region. PROTAC: ubiquitination databases record sites on it; its protein half-life has been measured.
Gene: Protein-coding gene on chromosome 3 (190,305,707 to 190,322,446, reverse strand). Ensembl gene ENSG00000163347.
Subcellular location: Cell junction, tight junction; Cell membrane; Basolateral cell membrane
Pathways (Reactome):
Cell-Cell communication: Tight junction interactions
Disease: Dengue Virus Attachment and Entry
Gene Ontology:
Molecular function: identical protein binding; protein binding; virus receptor activity; structural molecule activity
Biological process: bicellular tight junction assembly; cell-cell junction organization; establishment of skin barrier; positive regulation of cell migration; positive regulation of epithelial cell proliferation involved in wound healing; positive regulation of wound healing; protein complex oligomerization; calcium-independent cell-cell adhesion; cell junction maintenance; maintenance of blood-brain barrier; cellular response to butyrate; cellular response to lead ion; cellular response to transforming growth factor beta stimulus; cellular response to tumor necrosis factor; cellular response to type II interferon; establishment of blood-nerve barrier; establishment of endothelial intestinal barrier; liver regeneration; positive regulation of bicellular tight junction assembly; response to dexamethasone; response to ethanol; response to interleukin-18; response to lipopolysaccharide; response to toxic substance; symbiont entry into host cell; and 1 more
Cellular component: basolateral plasma membrane; bicellular tight junction; plasma membrane; protein-containing complex; tight junction; endosome membrane; membrane; apical plasma membrane; cell junction; cell-cell junction; lateral plasma membrane
Genetic constraint (gnomAD): Loss-of-function variants: 12 observed, 23.24 expected, observed/expected ratio (o/e) 0.52, 90% interval 0.33 to 0.84. The upper end of that interval is the gene's LOEUF score, 0.84, which puts it in group 3 of 6, group 1 being the genes least tolerant of losing a copy. Missense variants: 250 observed, 286.47 expected, observed/expected ratio (o/e) 0.87, 90% interval 0.79 to 0.97. Synonymous variants: 99 observed, 111.54 expected, observed/expected ratio (o/e) 0.89, 90% interval 0.75 to 1.05.
Homologues: Orthologues: chimpanzee CLDN1 (100% identical), macaque CLDN1 (99% identical), pig CLDN1 (95% identical), dog CLDN1 (93% identical), rabbit CLDN1 (92% identical), rat Cldn1 (91% identical), mouse Cldn1 (91% identical), guinea pig CLDN1 (83% identical), tropical clawed frog cldn1 (67% identical), zebrafish cldn1 (47% identical). Paralogues in human: CLDN7 (61% identical), CLDN19 (57% identical), CLDN3 (51% identical), CLDN9 (49% identical), CLDN14 (45% identical), CLDN4 (45% identical), CLDN5 (45% identical), CLDN6 (44% identical), CLDN17 (37% identical), CLDN2 (36% identical), CLDN8 (36% identical), CLDN20 (36% identical), and 10 more.
Diseases named in the same sentence as CLDN1 in open-access papers:
CLDN1 is named in the same sentence as 339 diseases in open-access papers, as found by Europe PMC text mining. Sharing a sentence is not in itself a finding about the gene and the disease. The quoted sentences say what the papers report.
colitis (141 papers, 2011 to 2026). Inflammation of the colon. "In a mouse model of intestinal claudin-1 overexpression, the animals were susceptible to colonic inflammation and showed impaired recovery following dextran sulfate sodium-induced colitis." (PMID 40071203, 2025). "IBD induces intestinal barrier dysfunction by reducing the expression of TJ proteins (Claudin-1, Occludin, and ZO-1) in colonic tissues, which consequently increases susceptibility to colitis." (PMID 40883849, 2025). "In contrast to FOS, while 2′-FL and 3′-FL effectively mitigated barrier dysfunction caused by IL-6 and symptoms of DSS-induced colitis, they bolstered the expression of tight junction proteins (ZO-1 and Claudin-1) to enhance intestinal barrier function." (PMID 41464891, 2025). "Expression of Claudin 1 diminishes upon chronic exposure to LPS challenge, whilst Claudin 2 expression is associated with protection of microbial-induced colitis." (PMID 39125663, 2024). "Weber and Pope reported that increased CLDN-1 expression in patient samples with inflammatory bowel disease is associated with early transformation stages of colitis-associated cancer." (PMID 35571126, 2022). "Surprisingly, mice with DSS-induced colitis who were administered HS showed normalized the expression levels of ZO-1, occludin and claudin-1, which are interepithelial TJ-associated proteins that play pivotal roles in gut homeostasis." (PMID 35025709, 2022). "DSS-induced colitis was also found to be associated with the decreased expression of Muc2, Claudin-1, and ZO-1." (PMID 33363184, 2020). "Loss of Zo-1, claudin-1, and occludin in Caco-2 cells and the colitis tissues was recovered after PRCC-1301 EVs treatment, as evidenced by immunofluorescence analysis." (PMID 33233771, 2020). "We found that DSS-induced colitis was associated with decreased expression of colonic claudin-1, claudin-3, claudon-5, claudin-7 and claudin-8, and also increased expression of colonic claudin-2." (PMID 22073304, 2011). "The loss of claudin-1 is consistent with impaired barrier integrity during colitis." (PMID 41211066, 2025). "In addition, claudin-1 overexpression causes increased susceptibility to DSS-induced colitis and inferior recovery from it." (PMID 38732595, 2024). "Therefore, constitutively high Occludin and Claudin-1 protein expression levels in the large intestine are likely to be attributed the reduced susceptibility to DSS-induced colitis in mPer2m/m mice." (PMID 24845399, 2014). "Occludin and Claudin-1 expressions in the large intestine are under the circadian control, which is associated with temporal regulation of colonic permeability and also susceptibility to colitis." (PMID 24845399, 2014). "In summary, we suggest that expressions of TJ proteins Occludin and Claudin-1 in the large intestinal epithelium are under control of the circadian clock, which is associated with temporal changes of colonic permeability and also susceptibility to colitis." (PMID 24845399, 2014). "Given that claudin-1 and claudin-2 play distinct roles in epithelial barrier integrity, the differential regulation of these proteins by IL-9 across various colitis models may underlie the context-dependent role of IL-9/Th9 cells in colitis development." (PMID 40771819, 2025). "Finally, the intestinal permeability was investigated, showing an increased permeability for 4 kDa FITC-dextran in colitis mice associated with a decreased mRNA level of junctional proteins Cldn1, Cldn2, Cdh1 and Ocln and an unaltered expression of scaffolding protein Zo1." (PMID 34248633, 2021). "Of interest, we have recently demonstrated that constitutive claudin-1 expression induces Notch signaling which in turn suppresses goblet cell differentiation and muc-2 expression to compromise the mucus barrier and thus increase susceptibility to colitis in Cld-1Tg mice." (PMID 24997475, 2014).
colitis (continued). "In fact, when compared to controls, a significant increase in colon weight-to-length ratio in the OVA+Cldn1−/− chimeras, which is a telltale sign of colitis, was observed." (PMID 41481333, 2026). "It was observed that ligustilide protected the colonic microvilli structure, narrowed the tight junction gap, and enhanced tight junction protein Claudin-1 and Occludin expressions in colitis mice." (PMID 40904624, 2025). "Claudin-1, also a tight junction protein, is vital in regulating the extent of colitis and colon cancer." (PMID 40405896, 2025). "In mice with DSS-induced colitis, the amounts of occludin and claudin-1 in their colon tissue dropped noticeably." (PMID 41247018, 2025). "DSS-induced colitis decreased the expression of intestinal tight junction proteins such as Occludin, Claudin-1, and ZO-1." (PMID 40842836, 2025). "Consistent with this, our earlier research also confirmed that VK supplementation elevated occludin, claudin-1, and ZO-1 expression in colitis mice." (PMID 41334343, 2025). "MBPs restored intestinal barrier function by upregulating the expression of ZO-1 and claudin-1 proteins within the colonic tissue of mice with DSS-induced colitis, thereby treating UC." (PMID 40282764, 2025). "To examine the therapeutic effects of NAF AuNRs on epithelial barrier function in colitis, we analyzed the expression of ZO-1, claudin-1, and occludin, the critical components of TJs, by RT-PCR, WB, and IF." (PMID 40255504, 2025). "In parallel, western blotting of colon tissue lysates demonstrated that DSS colitis caused a significant increase in PSME2 protein, accompanied by a decrease in the tight junction protein claudin-1." (PMID 41211066, 2025). "AMK polysaccharides increase the expression of tight junction proteins, such as ZO-1, Occludin, and Claudin-1, to strengthen the intestinal epithelial barrier in patients with conditions such as colitis and diarrhea." (PMID 40144663, 2025). "The results revealed a lower percentage of brownish-yellow areas corresponding to Claudin-1, ZO-1, and Occludin in the Gpr81−/− colitis mice, indicating a reduced expression of TJ proteins." (PMID 38474712, 2024). "In this study, we demonstrated that in colitis-affected animals, OPs enhanced the quantity of goblet cells and upregulated the production of mucin and the tight junction protein claudin-1." (PMID 38892524, 2024). "In the nobiletin-treated non-colitis group, claudin-1 was predominantly expressed on the surface epithelium and in the epithelial lining of the superficial parts of the glands." (PMID 39334888, 2024). "Expression of the claudin-1, -2, and -4 protein isoforms was altered in the inflamed colons compared to the non-colitis controls." (PMID 39334888, 2024). "And VSL#3 was also shown to increase the expression of tight junction genes, Zo-1, occludin, and claudin-1 in the colon tissue in TNBS-induced colitis mice." (PMID 39849930, 2024). "Previous research has demonstrated that FICZ effectively counteracted the decrease in the expression levels of ZO-1, occludin, and claudin-1 induced by DSS in mice colitis, thereby enhancing the integrity of the intestinal barrier." (PMID 38473179, 2024). "Specifically, DSS-induced colitis markedly decreased the expression of ZO-1, occludin, and claudin-1 and dramatically increased the expression of claudin-2 at the mRNA levels; nevertheless, the abnormal expression was corrected by the UTI treatment." (PMID 38397811, 2024). "Meanwhile, colonic TJ proteins ZO-1, MUC2, claudin-1, and occludin in colitis mice pre-treated with B. tequilensis YB-2 significantly increased their expression levels and played a critical part in maintaining the epithelial barriers of the mouse colon." (PMID 38998101, 2024). "SCFAs enhance barrier integrity via the claudin-1 pathway, elevate IL-10 production through activating Treg differentiation, and improve the efficacy of broad antibiotic therapy in colitis." (PMID 37509556, 2023).
colitis (continued). "It has previously been shown that suppressing both MAPK pathways contributed to the amelioration of chemically induced murine colitis and the restoration of the intestinal barrier by elevating tight junction expression (CLDN1, ZO-1, OCLN)." (PMID 37174625, 2023). "The results showed that the ZO-1, Occludin and Claudin-1 proteins were decreased in the intestines of DSS-induced colitis mice, and both Occludin and Claudin-1 levels were significantly restored after SCP treatment." (PMID 38004208, 2023). "The result showed that Occludin and Claudin-1 mRNA were significantly upregulated in Parkin-/- mice, suggesting that loss of Parkin has a protective effect in DSS-induced colitis." (PMID 37056928, 2023). "In colon tissue, the gene expressions of Claudin-1, Occludin and ZO-1 proteins were considerably suppressed in colitis mice but markedly increased in the P10 group." (PMID 37761037, 2023). "Both the concentration and expression levels of Claudin-1 increased after S. cerevisiae QHNLD8L1 treatment in mice with colitis (p < 0.05)." (PMID 37047694, 2023). "mRNA expression of Cldn1 and Cldn2 was significantly altered in control Muc13−/− mice compared to wildtypes and during the course of colitis." (PMID 37174625, 2023). "Claudin-1, claudin-4 and claudin-7, which are normally expressed in the colon for TJ sealing, are observed reduced in acute colitis, CD and colitis patients." (PMID 36767519, 2023). "In the present study, the inosine intervention dramatically up-regulated the expressions of ZO-1, occludin, and claudin-1 in mice with colitis, which partly explained the alleviative efficacy of inosine on the intestinal barrier functions in mice with colitis." (PMID 37762155, 2023). "The colitis group had higher gene expression of claudin-1 and claudin-2 compared to the Sham group (8.12±1.79 vs 0.94±0.16 and 3.51±0.67 vs 1.01±0.13, respectively, P<0.05)." (PMID 37909497, 2023). "NK151, NK173, and NK175 alleviated iGm-induced colitis: they decreased IL-1β and IL-6 expression, while IL-10 and claudin-1 expression increased." (PMID 35631220, 2022). "Compared with the control group, the protein expression of CLDN1 was significantly increased in TNBS-induced colitis and downregulated in SBP and MES treatment groups." (PMID 35571126, 2022). "In the development of colitis, the expression of tight junction proteins, such as ZO-1, occludin, and claudin-1, is negatively correlated with increased intestinal barrier permeability." (PMID 36590200, 2022). "Mouse models with altered expression of specific claudin genes either develop spontaneous mucosal inflammation (CLDN7 knockout) or exhibit enhanced (CLDN1 overexpression, or CLDN2 knockout) or reduced (CLDN2 overexpression) susceptibility to induced colitis." (PMID 35805947, 2022). "Since increased barrier permeability plays an important role in IBD, we stained for Cldn1 in Bmal1+/+ controls and Bmal1-/- mutant tissue with colitis." (PMID 35223537, 2022). "Decreased expression of Cldn1 and Ocln can also be related to monocyte infiltration and inflammation, such as in mouse models of colitis." (PMID 35248004, 2022). "The decreased claudin-1 expression by BLIDF supplementation suggests that BLIDF can alleviate colitis severity in DSS-treated mice." (PMID 33807544, 2021). "In the chronic DSS-induced colitis model, DSS caused disruption of the epithelium and thereby a loss of TJ proteins, e.g., Claudin-1 (CLDN1)." (PMID 33668818, 2021). "Mice with overexpression of CLDN1 are more prone to colitis and demonstrate slower recovery following the DSS treatment." (PMID 34444876, 2021). "In this study, it was found that BL increased the expression of Claudin-1, Occludin, and ZO-1 in the intestines of colitis mice." (PMID 33954162, 2021). "We found that occludin, ZO-1, and claudin-1 expression levels in the colon were significantly reduced in colitis mice, and especially claudin-1." (PMID 32855978, 2020).